MIR526B (microRNA 526b)
Synonyms: hsa-mir-526b; MIRN526B
Gene: MicroRNA gene on chromosome 19 (53,694,393 to 53,694,475, forward strand). Ensembl gene ENSG00000207580.
Gene Ontology:
Biological process: miRNA-mediated post-transcriptional gene silencing
Diseases named in the same sentence as MIR526B in open-access papers:
MIR526B is named in the same sentence as 2 diseases in open-access papers, as found by Europe PMC text mining. Sharing a sentence is not in itself a finding about the gene and the disease.
MIR526B shares sentences with these, for which no sentence is quoted: breast carcinoma (1 paper); Tumour (1).